IL9 (interleukin 9)
Diseases named in the same sentence as IL9 in open-access papers (continued):
Sharing a sentence is not in itself a finding about the gene and the disease.
inflammatory bone disease (2 papers, 2021 to 2023). "Very recently, we have shown that IL-9 facilitates differentiation of human myeloid cells into osteoclasts in RA, an inflammatory bone disease." (PMID 36732282, 2023). "Our study strongly suggest that IL-9 has the potential to mediate structural damage in inflammatory bone diseases such as RA by the enhancing the differentiation of osteoclasts, its bone resorptive capacity, and by modulating the expression of MMPs." (PMID 34638736, 2021). "In addition, we showed that high concentrations of IL-9 enhanced the frequency of IL-17 producing T cells, which is a known player in mediating inflammatory bone disorders." (PMID 36732282, 2023). "Thus, our study provides a possible mechanism by which IL-9 can impair the functions of Treg cell during inflammatory bone disease leading to excessive inflammation and osteoclastogenesis." (PMID 36732282, 2023).
kidney damage (2 papers, 2020 to 2025). "Less-characterized interleukins such as IL-3, IL-5, IL-9, and IL-27 demonstrate dual or context-dependent roles, particularly in shaping immune tolerance and tissue-specific complications such as nephropathy and neuropathy." (PMID 40804870, 2025). "Thus, we could improve the resolution of inflammation and reduce kidney damage via inhibiting the decrease of IL-9." (PMID 32194547, 2020).
Lewis lung carcinoma (2 papers, 2017 to 2022). "To test if the regulation by IL-9 on lung macrophages is unique to B16 lung tumor models, we i.v. injected mice with Lewis lung carcinoma (LLC) tumor cells." (PMID 35778404, 2022).
lung disease (2 papers, 2017 to 2022). "In conclusion, IL-9 and MC may have an important role in the pathogenesis of lung disease and inflammation in CF." (PMID 28090087, 2017).
lymphoid neoplasm (2 papers, 2010 to 2021). A neoplasm composed of a lymphocytic cell population which is usually malignant (clonal) by molecular genetic and/or immunophenotypic analysis. "On the other hand several of the IL-9/NPM-ALK+ mice developed plasmocytomas, a lymphoid neoplasm that is a relatively frequent AHNMD in human SM." (PMID 21297223, 2010).
mycosis fungoides (2 papers, 2023 to 2024). Classical mycosis fungoides is the most common type of mycosis fungoides (MF), a form of cutaneous T-cell lymphoma, and is characterized by slow progression from patches to more infiltrated plaques and eventually to tumors. "Previous studies conducted in Mycosis fungoides and Sézary syndrome have shown that SATB1 can influence the expression of IL5 and IL9." (PMID 39195213, 2024).
NK/T-cell lymphoma (2 papers, 2014 to 2016). "However, the relationship between IL-9 and the clinicopathological features of extranodal NK/T-cell lymphoma is less well established." (PMID 24722378, 2014). "In fact, some studies have confirmed that IL-9 could act in an autocrine manner in ALCL and NKT-cell lymphomas." (PMID 27364124, 2016).
non-small cell lung carcinoma (2 papers, 2022). A group of at least three distinct histological types of lung cancer, including non-small cell squamous cell carcinoma, adenocarcinoma, and large cell carcinoma. "IL-9-producing tumor-infiltrating lymphocytes and Treg subsets drive immune escape of tumor cells in non-small cell lung cancer." (PMID 35966889, 2022). "In this study, we aimed for characterizing the expression and function of IL-9, a cytokine with immune-regulatory functions, in non-small cell lung cancer (NSCLC)." (PMID 35514957, 2022).
osteoarthritis (2 papers, 2021 to 2024). A noninflammatory degenerative joint disease occurring chiefly in older persons, characterized by degeneration of the articular cartilage, hypertrophy of bone at the margins and changes in the synovial membrane. "Furthermore, IL-9 and IL-9 producing CD3+ T cells are increased in the synovial fluid of PsA when compared to osteoarthritis patients." (PMID 33869291, 2021).
pertussis (2 papers, 2021). A contagious bacterial respiratory infection caused by Bordetella pertussis. "CD4+ T cells secreting both IL-9 and IL-17 have been shown to be associated with pertussis-specific responses after the vaccination." (PMID 34200795, 2021).
Pleural effusion (2 papers, 2015 to 2021). The presence of an excessive amount of fluid in the pleural cavity. "Thus, the diagnostic accuracy of CD4+IL-9+ frequency in pleural effusion was 67.04% (59/88)." (PMID 34925358, 2021). "In conclusion, current data suggest that the determination of ADA, CD4+IL-9+, and Treg cells in pleural effusion may be an important diagnosis marker for TPE." (PMID 34925358, 2021). "The frequency of CD4+IL-9+, CD4+IL-17+, CD4+ IL-22+, and CD4+CD25+FOXP3+ cells in the pleural effusions." (PMID 34925358, 2021). "The differentiation of Th9 cells from CD4+ cells that were isolated from the pleural effusion or blood of these patients was dependent on TGF-β, and the production of IL-9 in the cultures was amplified by the addition of IL-4, IL-1β, and IL-6." (PMID 26495323, 2015). "It was also suggested in the same work that IL-9 may be, along with TGF-β, promoting the differentiation of Th17 cells because a positive correlation was observed between the number of Th9 and Th17 cells in the pleural effusion." (PMID 26495323, 2015).
preeclampsia (2 papers, 2021 to 2023). Preeclampsia is a hypertensive disorder of pregnancy that is characterized by new-onset hypertension with proteinuria presenting after 20 weeks of gestation, and depending on mild or severe forms may initially present with severe headache, visual disturbances, and hyperreflexia. "We found that the growth regulated oncogene A (GROA) and interleukin-9 (IL-9) were associated with the development of pregnancy hypertension, whereas interleukin-10 (IL-10) and hepatocyte growth factor (HGF) were linked to the occurrence of preeclampsia." (PMID 38362587, 2023).
relapsing-remitting MS (2 papers, 2024). "Notably, a recent clinical study uncovered a significant positive correlation between IL-9 and TREM2 levels in the cerebrospinal fluid (CSF) of relapsing-remitting MS patients." (PMID 38745307, 2024).
Renal Dysfunction (2 papers, 2020). "In some studies, renal dysfunction was associated with a significant increase of serum cytokines, including IL-9." (PMID 32587468, 2020).
respiratory infections (2 papers, 2017). "The variant with the most significant association is near IL9, a gene with a substantial role in airway inflammation, bronchial asthma, and other respiratory infections." (PMID 28628665, 2017).
rheumatic diseases (2 papers, 2015 to 2022). "Very few studies in recent years have evaluated IL-9 in the context of rheumatic diseases such as SLE and RA." (PMID 26078482, 2015). "Despite the lack of reports on the IL9 rs2069885 polymorphism in rheumatic diseases, there is a number of studies highlighting the role of IL-9 itself in rheumatic diseases." (PMID 36361964, 2022). "Some of the performed studies regarding IL-9 role in the pathogenesis of rheumatic diseases suggest that this cytokine might contribute to their development." (PMID 36361964, 2022). "The exact molecular mechanism of IL-5 and IL-9 action in the pathogenesis of rheumatic diseases has not been well described to date." (PMID 36361964, 2022).
severe combined immunodeficiency (2 papers, 2022 to 2024). Severe combined immunodeficiency (SCID) comprises a group of rare monogenic primary immunodeficiency disorders characterized by a lack of functional peripheral T lymphocytes resulting in early-onset severe respiratory infections and failure to thrive. "JAK3 knock-out mice are found to develop severe combined immunodeficiency (SCID) due to impairment in B cell development associated with IL-2, IL-4, IL-7, IL-9, and IL-15 receptor signaling." (PMID 38380328, 2024). "In this study, we report a 4-month-old boy with T−B+NK− severe combined immunodeficiency (SCID) due to a novel mutation in exon 2 of IL2RG, the gene encoding the interleukin (IL) common gamma chain (γc) of the cytokine receptors for IL-2, IL-4, IL-7, IL-9, IL-15, and IL-21." (PMID 35498802, 2022).
Ss (2 papers, 2016 to 2018). "We hypothesized that Ss infection would be associated with alterations in memory T cell subset distribution, alterations that could be reflective of changes in IL-2, IL-4, IL-7, IL-9 and IL-15." (PMID 29795573, 2018). "This confirms our previous data demonstrating elevated IL-4 and IL-9 responses in Ss infection and its reversal following anthelmintic therapy." (PMID 29795573, 2018). "Moreover, our data also indicate that the enhanced frequencies of Th9 cells is reflected in elevated expression of IL-9 on a per cell basis in Ss infections." (PMID 26730582, 2016).
ST Elevation Myocardial Infarction (2 papers, 2013 to 2015). A myocardial infarction that produces elevation in the ST segments of the ECG. "(ii) On admission, patients with acute ST-elevation myocardial infarction (STEMI) (n = 42) had markedly raised IL-9 plasma levels which gradually declined during the first week post-MI." (PMID 24023645, 2013).
tuberculous pleurisy (2 papers, 2012 to 2021). "Similarly, we found a significant increase in the plasma levels of IL-6 and IL-9 in patients with active pulmonary tuberculosis and tuberculous pleurisy." (PMID 23028695, 2012). "Our data suggest that compared to patients without TPE, patients with tuberculous pleurisy have a two-fold higher chance of being CD4+IL-9+ T cell positive." (PMID 34925358, 2021). "Similarly, if a patient has a negative result of CD4+IL-9+ T cells, he would have a 0.18% chance of being a tuberculous pleurisy patient." (PMID 34925358, 2021).
Type I hypersensitivity reaction (2 papers, 2021 to 2024). "In type I hypersensitivity reactions, low concentrations of the allergen (via inhalation or exposure in the gastrointestinal tract) presented in the presence of interleukin (IL)-4, IL-5, IL-9, and IL-13 are responsible for the dominant Th2 response." (PMID 34099042, 2021).
viral myocarditis (2 papers, 2018 to 2021). Myocarditis that is caused by an infection with a viral agent. "Th9 and Tc9-secreting IL-9 still strongly inhibited coxsackie virus B3 replication without induction of apoptosis in cardiomyocytes, although the viral myocarditis did not mainly contribute to differentiation and proliferation of Th9 cells." (PMID 34177894, 2021).
X-linked severe combined immunodeficiency (2 papers, 2014 to 2021). "X-linked severe combined immunodeficiency (X-SCID) is caused by mutations of IL2RG, the gene encoding the interleukin common gamma chain (IL-2Rγ or γc) of cytokine receptors for interleukin (IL)-2, IL-4, IL-7, IL-9, IL-15, and IL-21." (PMID 34248995, 2021). "X-linked severe combined immunodeficiency (XSCID) is caused by a genetic mutation within the common gamma chain (γc), an essential component of the cytokine receptors for interleukin (IL)-2, IL-4, IL-7, IL-9, IL-15, and IL-21." (PMID 25025687, 2014).
acute kidney injury (1 paper, 2020). Sudden and sustained deterioration of the kidney function characterized by decreased glomerular filtration rate, increased serum creatinine or oliguria. "Here, we investigated the key role of IL-9 as a regulator of protective mechanisms in CP-induced acute kidney injury (AKI)." (PMID 32194547, 2020). "Due to conflicting reports in the literature, the contribution of IL-9 to disease is unclear, especially in the context of CP-induced acute kidney injury (AKI)." (PMID 32194547, 2020).
alopecia areata (1 paper, 2021). Loss of scalp and body hair involving microscopically inflammatory patchy areas. "To date, increased concentrations of serum IL-9 in patients with alopecia areata compared to healthy controls have only been reported in one study." (PMID 34943905, 2021). "The role of the serum IL-9 in alopecia areata needs to be confirmed in further studies." (PMID 34943905, 2021).
amebiasis (1 paper, 2017). A parasitic infectious disorder caused by amoebas. "In order to describe the immune response induced by IL-25 during amebiasis, we measured IL-4, IL-5, and IL-9 by enzyme-linked immunosorbent assay (ELISA) from cecal tissue lysates of mice after E. histolytica challenge with or without rIL-25 treatment." (PMID 28246365, 2017).
aneurysm (1 paper, 2019). Bulging or ballooning in an area of an artery secondary to arterial wall weakening. "Between the two experimental groups, IL-9, IL-12(p40), RANTES, and VEGF also showed significantly higher levels when in the presence of aneurysm-containing serum than in the presence of aneurysm-free serum (p = 0.005, 0.005, 0.005, and 0.0001, respectively)." (PMID 31428158, 2019).
ankylosing spondylitis (1 paper, 2022). An autoimmune chronic inflammatory disorder characterized by inflammation in the vertebral joints of the spine and sacroiliac joints. "Significant relationships between the IL5 rs2069812 and IL9 rs2069885 polymorphisms and response to anti-TNF treatment, expressed by the Bath Ankylosing Spondylitis Disease Activity Index (BASDAI) were observed." (PMID 36361964, 2022).
anthrax (1 paper, 2015). "Thus, cutaneous anthrax induces a broad T cell memory response characterized not only by the presence of Th1 cytokines IFNγ and TNFα, but also Th2 (IL-5 and IL-13), Th17 (IL-17/IL-22), Th22 (IL-22) and Th9 (IL-9) cytokines and a potentially regulatory IL-10 response." (PMID 26075052, 2015).
Atrophy (1 paper, 2020). Any weakening or degeneration, especially through lack of use. "One theory is that eosinophils are mediated by specific types of T-helper cells that result in higher cytokine production, including TNF-α and IL-9, and this contributes to interstitial atrophy, irreversible fibrosis, and eventually ESKD." (PMID 31931743, 2020).
bladder tumor (1 paper, 2019). "IL-9 was not studied in patients with urological cancers to date, yet absence of IL-9 mRNA was reported in bladder tumor cell lines." (PMID 30984190, 2019).
Cachexia (1 paper, 2018). Severe weight loss, wasting of muscle, loss of appetite, and general debility related to a chronic disease. "Clinically, patients with increased serum IL-9 levels have been shown to have a worsened prognosis and higher levels of systemic IL-9 were also associated with cachexia and lower hemoglobin concentrations in IBD patients." (PMID 29910812, 2018).
childhood asthma (1 paper, 2021). "IL-9, a regulator of haematopoietic cells, is associated with childhood asthma." (PMID 34280516, 2021).
chlamydial infection (1 paper, 2015). "Further understanding on the reason of quick decline of IL-9 and intervention to maintain or enhance IL-9 may provide a new way to enhance protective immunity or reduce immunopathology in chlamydial infection." (PMID 25646821, 2015). "The quick decline of IL-9 responses may be related to a feedback mechanism which quickly inhibits IL-9 production thus being used as escape strategy taken by chlamydia." (PMID 25646821, 2015). "However, the data from our present study did not support either role of IL-9 in chlamydial infection." (PMID 25646821, 2015).
cholestasis (1 paper, 2024). Impairment of the bile flow caused by obstruction within the liver, or outside the liver in the bile duct system. "IL-9 was found to stimulate the growth of Interstitial cells of Cajal (ICC) and support its functions, potentially resulting in enhanced gallbladder motility and decreased cholestasis, which helps to reduce the occurrence of gallbladder polyps." (PMID 39439893, 2024).
Chronic colitis (1 paper, 2021). A chronic inflammatory disease of the large intestine (colon, cecum and rectum). "Wang and Zhao’s research showed that tumor necrosis factor-like ligand 1A could destroy the mucosal barrier by promoting Th9 and IL-9 overexpression in mice with chronic colitis." (PMID 33941281, 2021).
chronic mucocutaneous candidiasis (1 paper, 2019). "IL-9 is reported to have a defect in patients with chronic mucocutaneous candidiasis 43, but its role in PCP remains unclearly defined." (PMID 31588187, 2019).
chronic myelogenous leukaemia (1 paper, 2023). "Herein, the authors show in an inducible murine model of chronic myelogenous leukaemia that a systemic inflammatory state can trigger IL-33- mediated IL-9 production that leads to small intestinal remodelling and PCM." (PMID 38042840, 2023).
chronic spontaneous urticaria (1 paper, 2024). "Role of complement fraction 5a (C5a), interleukin (IL)-9, and apolipoprotein (apo) A-IV as biomarkers of disease severity and antihistamine response in chronic spontaneous urticaria (CSU) remains elusive." (PMID 38482455, 2024).
Cm (1 paper, 2015). "We found lung Cm infection did induced IL-9 production by CD45+ and more specifically CD4+ T cells (CD4+CD3ε+)." (PMID 25646821, 2015).
Cognitive impairment (1 paper, 2023). Abnormal cognition is characterized by deficits in thinking, reasoning, or remembering. "IL-9, a cytokines associated with proliferation and survival of T cells, was lower in women with cognitive impairment." (PMID 37901041, 2023). "However, at the individual cytokine level, we also found lower levels of LT-α (also known as TNFβ) and IL-9, in women with cognitive impairment." (PMID 37901041, 2023).
colonic polyp (1 paper, 2024). "Using univariable MR analyses and Bayesian model averaging, we identified MIG, IL-18, and IL-2ra as the top three causes of gastric polyp, MIP1b and IL-6 as the top two protective factors for colonic polyp, and an inverse association between IL-9 and gallbladder polyp." (PMID 39439893, 2024).
colorectal tumours (1 paper, 2022). "As IL-6 is a protumorigenic cytokine that is highly elevated in colitis-associated neoplasias, we checked the correlation between Il-6 and Il-9 mRNA levels in colorectal tumours of wild-type mice." (PMID 35793807, 2022). "To analyse the cell type producing IL-9 in colorectal tumours more closely, we took IL-9 citrine reporter mice." (PMID 35793807, 2022). "We found that mainly CD4+ T cells, rather than CD19+ B cells and CD8+ T cells, produce IL-9 in colorectal tumours." (PMID 35793807, 2022).
coronary atherosclerosis (1 paper, 2013). Atherosclerosis of the coronary vasculature. "The findings so far suggested increased systemic expression of IL-9 in both carotid and coronary atherosclerosis." (PMID 24023645, 2013). "Here we report for the first time increased levels of both IL-9 and IL-9R in patients with carotid and coronary atherosclerosis." (PMID 24023645, 2013). "We examined this hypothesis by various experimental approaches including studies on the expression of IL-9 and IL-9R in patients with carotid and coronary atherosclerosis." (PMID 24023645, 2013).
Cryptococcus neoformans infection (1 paper, 2022). "In CM patients with Cryptococcus neoformans infection, IL-1ra, IL-9, and VEGF were significantly elevated in immunocompetent cases." (PMID 36032125, 2022).
cutaneous candidiasis (1 paper, 2018). Candidiasis of the skin manifested as eczema-like lesions of the interdigital spaces, perleche, or chronic paronychia. "For instance, Candida induces IL-9 in a skin-tropic T cell population, suggesting that IL-9 might be a key player also in cutaneous candidiasis with a possible involvement of MC." (PMID 30515173, 2018).
deafness (1 paper, 2019). An inherited or acquired condition characterized by the complete loss of the ability to hear from one or both ears. "In contrast, IL-13 and IL-9 concentrations were higher in patients with complete deafness (surditas, SDT) compared to patients with residual hearing (*p < 0.05) although statistical significance was missed for IL-9 (p = 0.058)." (PMID 31293504, 2019).
diabetic cardiomyopathy (1 paper, 2016). Diabetic cardiomyopathy is a disorder of the heart muscle in people with diabetes. "However, the role of IL-9 in diabetic cardiomyopathy remains unclear." (PMID 26972749, 2016).